INS (insulin)
Diseases named in the same sentence as INS in open-access papers (continued):
Sharing a sentence is not in itself a finding about the gene and the disease.
Obesity (continued). "Some natural plant extracts, such as naringenin and β-carotene, have the potential to safely improve obesity by driving lipolysis and enhancing insulin sensitivity." (PMID 38921478, 2024). "Better understanding of mechanisms describing how adipose eosinophils modulate circulating insulin, adipose inflammation, and airway hyperresponsiveness is a novel and promising avenue for research in obesity and obesity-related asthma." (PMID 39316677, 2024). "Induced obesity with a high grain diet for 5 months resulted in ID (increased glucose and insulin concentrations, and higher area under a glucose curve following an OGT) after 90 days." (PMID 38473112, 2024). "The present study demonstrated the insulin-sensitizing, glucose-regulating, anti-obesity, and anti-hyperlipidemic properties of Furocyst in women with PCOS, and the overweight and obese seemed to be most benefitted from the drug." (PMID 39734992, 2024). "Vitamin D supplementation appears to impact obesity-related factors such as blood pressure, glucose levels, and insulin resistance." (PMID 39092232, 2024). "In conclusion, resveratrol appears to provide beneficial effects in insulin-stimulated glucose metabolism in myotubes from lean individuals and individuals with severe obesity." (PMID 38324260, 2024). "We performed metabolic phenotyping related to insulin levels, glucose handling, and obesity in male DKO mice along with single knockout of Znt8 or Sst mice and the WT control." (PMID 39567934, 2024). "Research has shown that resveratrol supplementation can mimic the effects of calorie restriction in humans with obesity, potentially improving metabolic profiles and insulin sensitivity." (PMID 38732542, 2024). "Pima Indians who have high rates of obesity also have significantly higher fasting insulin and display a higher amplitude insulin response to a glucose load." (PMID 38212644, 2024). "Changes in metabolic control, insulin insensitivity, inflammation, and weakened immune response are key features shared by obesity and aging." (PMID 39429354, 2024). "Overall, given PTP1B's critical role in insulin and leptin signaling, it is considered an excellent target for treating obesity and diabetes." (PMID 39238503, 2024). "BPA activates PPAR-y, which contributes to the sensitization of adipocytes to insulin, altering blood glucose homeostasis and favoring the development of obesity." (PMID 39519574, 2024). "This ongoing low-grade inflammation is thought to contribute to changes in insulin-glucose homeostasis related to obesity." (PMID 39735643, 2024). "It has also been reported that chlorpyrifos (5 mg/kg) can promote obesity and insulin resistance by increasing gut inflammation in mice." (PMID 39312839, 2024). "In line with our findings, it has been reported that obesity promotes bile acid synthesis to facilitate body fat absorption and regulate insulin secretion by activating many signaling pathways." (PMID 39261864, 2024). "The obesity and diabetic traits were confirmed by measuring the BMI and amount of adipose, as well as via two glucose assays (fasting and random) and one insulin assay." (PMID 39621609, 2024). "Obesity can disrupt insulin signaling pathways, leading to insulin resistance, increased fat formation through triglyceride hydrolysis into fatty acids, increased sympathetic activity, and dysregulation of the renin-angiotensin-aldosterone system." (PMID 39044934, 2024). "Obesity‐induced inflammation activates various signaling pathways, impairs insulin signaling, and promotes the release of proinflammatory mediators such as TNF‐α, IL‐1β, and IL‐6, all of which contribute to IR." (PMID 38812572, 2024). "Overweight and obesity can exacerbate over the course of a person’s life due to aggressive insulin treatment, excessive insulinization, frequent hypoglycemia, and defensive snacking." (PMID 39768947, 2024).
Obesity (continued). "Other studies have suggested that hyperinsulinemia precedes TPP attacks and that patients with TPP exhibit a higher prevalence of obesity and lower insulin sensitivity than those with simple thyrotoxicosis." (PMID 39088436, 2024). "As a complementary approach, ex vivo assays were performed to deepen into the involvement of insulin in obesity-related erythroid disturbances, discarding potential confounding interferences derived from the complex systemic environment." (PMID 39261864, 2024). "Parallels have been drawn between human literature and beef cattle literature where fasting concentrations of insulin increase with obesity in humans or BW in beef steers." (PMID 38456567, 2024). "Obesity is associated with severe VAT transcriptome dysregulation, which results in the overexpression of pro-inflammatory genes, altered insulin signaling pathways, and downregulation of fertility-related genes." (PMID 39857648, 2024). "It has been observed that their dysfunction is connected with metabolic syndrome, including insulin signaling downregulation and hastened development of hyperlipidemia, obesity, and hypertension." (PMID 38250153, 2024). "Conversely, the low levels of circulating osteoglycin seen during obesity act dually to both reduce food intake and reduce insulin responsiveness, glucose uptake, and, as a consequence, increase blood glucose." (PMID 39588310, 2024). "This suggests that this treatment reduces obesity, improves insulin sensitivity, and attenuates the progression of atherosclerosis by improving inflammation." (PMID 39409124, 2024). "Banana resistant starch showed anti-obesity effects by modulating lipid and glucose metabolism, lowering leptin and insulin levels and enhancing healthy gut bacteria." (PMID 39568514, 2024). "A previous study confirmed that the upregulation of C2 is positively correlated with obesity and hyperinsulinemia in subcutaneous adipose tissue and adipocytes and negatively correlated with the expression of insulin signaling-related genes." (PMID 39518882, 2024). "The research mainly focused on “obesity,” “activation,” and “inflammation” with “insulin resistance” being the most frequent term." (PMID 39465505, 2024). "Regular physical exercise is an effective therapeutic strategy for improving insulin sensitivity by multiple mechanisms: it has the potential to increase cellular sensitivity to insulin and to reduce inflammation and obesity." (PMID 38791525, 2024). "The insulin-glucagon bipolar axis represented in the form of the insulin:glucagon ratio (IGR) is therefore an interesting variable to study in people with obesity and with different glucose tolerance states." (PMID 38665134, 2024). "Adipose tissue depot and metabolic state have been shown to impact the acetylome in human subcutaneous and omental adipose tissue from lean, normal-glycaemic and insulin-resistant donors with obesity." (PMID 38840842, 2024). "Activation of AMPK has been associated with beneficial effects on metabolism, such as improving insulin sensitivity and ameliorating obesity." (PMID 38534314, 2024). "Another study in youth with overweight/obesity found greater benefits from diverse, multicomponent exercises on insulin markers, reinforcing the importance of multifaceted physical training for glycaemic regulation across populations." (PMID 38951907, 2024). "Among these, proteins such as major royal jelly proteins (MRJPs) have been shown to improve insulin sensitivity and reduce obesity-related inflammation, highlighting their potential role in weight management." (PMID 39339774, 2024). "The reduced ability of insulin to suppress lipolysis in obesity was most evident in response to the low-dose insulin infusion." (PMID 38602778, 2024). "Previous studies have demonstrated that the augmentation of UCP-1 through genetic modifications or the administration of pharmacological substances can lead to a decrease in obesity and an enhancement in insulin sensitivity." (PMID 38702594, 2024).
Obesity (continued). "Lipid accumulation and fatty streaks develop in many adults, with obesity accelerating atherosclerotic changes through mechanisms such as insulin resistance and inflammation." (PMID 39513280, 2024). "This systematic review and meta-analysis demonstrated that consumption of plant-based diets resulted in improvements in insulin sensitivity assessed by HOMA-IR and fasting insulin compared with a control diet in people with overweight/obesity." (PMID 38999858, 2024). "Oral administration of pasteurized A. muciniphila significantly reduced insulinemia, improved insulin sensitivity, and reduced plasma total cholesterol in patients with obesity-related metabolic disorders compared to placebo." (PMID 38283696, 2024). "As insulin-sensitive tissues, adipose tissue and liver are substantially influenced by obesity at both biomolecular and functional levels." (PMID 38674824, 2024). "Hypertrophic adipocytes, as consequence of visceral fat expansion during obesity, secrete inflammatory molecules which, coupled with the reduced insulin-mediated lipolysis suppression, results in increased release of circulating free fatty acids (FFAs)." (PMID 38133765, 2024). "The previous study has reported that insulin signaling within the pituitary plays an important role in ovulation disorders related to obesity induced by HFD." (PMID 39906039, 2024). "Insulin sensitivity and LPL expression are also linked to another factor which can be altered in obesity: the prevalence of the different types of fibers in skeletal muscle." (PMID 38674801, 2024). "Accordingly, LGZG treatment reduced serum insulin levels, which tended to increase in obesity (p < 0.05), and significantly reduced HOMA-IR in comparison with the OB group (p < 0.05)." (PMID 39156823, 2024). "This outcome carries substantial clinical relevance, given the close association between reduced adipose tissue mass and improvements in insulin sensitivity and dyslipidemia, both of which are paramount in addressing obesity-related comorbidities." (PMID 38474161, 2024). "For example, kaempferol was shown to exert anti-obesity effects because it increased insulin secretion in beta cells." (PMID 39456179, 2024). "Supplementation with 2-oxoglutarate prevents diet-induced obesity and improves glucose tolerance and insulin sensitivity." (PMID 39687851, 2024). "Adipose tissue develops resistance to insulin and leptin and is the source of altered hormone and molecule release for adiponectin, which worsens obesity-related cardiovascular disease." (PMID 38899161, 2024). "IP6K1 knockout mice show increased insulin sensitivity and resistance to obesity, indicating a novel therapeutic target for combating insulin resistance." (PMID 39125938, 2024). "Protein-rich formulas are considered a factor that can accelerate plasma insulin levels and lead to the release of insulin-like growth factor-1, consequently resulting in weight gain and later obesity." (PMID 39759652, 2024). "The REDOX model predicts that ingesting ROS-generating obesogens will promote obesity by stimulating excess nutrient intake, insulin secretion, and fat storage or inhibiting energy efficiency adaptations." (PMID 38212644, 2024). "Clinical manifestations of PCOS, such as anovulation, infertility, and obesity, involve dysfunction in the hypothalamic-pituitary axis, ovarian function, and insulin activity." (PMID 38737668, 2024). "Our analysis was adjusted for potentially important factors associated with risk for pancreatic cancer, such as smoking, obesity, and history of pancreatitis before GLP-1RA or basal insulin treatment." (PMID 38175642, 2024). "NEW & NOTEWORTHY A physiologically relevant dose of resveratrol increases insulin-stimulated glucose oxidation and glycogen synthesis in myotubes from individuals with severe obesity." (PMID 38324260, 2024).
Obesity (continued). "The authors reviewed 35 studies involving 1,550 children and adolescents aged 9 to 18 years with overweight and obesity, analyzing the effects of exercise training on fasting glucose, fasting insulin, HOMA-IR, and body weight." (PMID 39337980, 2024). "The women with severe obesity exhibited an elevated BMI, fasting insulin, and HOMA-IR compared with the lean subjects." (PMID 38324260, 2024). "The patient was having grade 2 obesity, insulin-dependent, on hemodialysis, and had obstructive sleep apnea on bilevel positive airway pressure." (PMID 39606037, 2024). "Remarkably, in the DIO model, Azpg1 overexpression within hypothalamic ObRb neurons led to notable alleviation of obesity-like phenotypes and metabolic dysfunction, including increased insulin sensitivity." (PMID 38643150, 2024). "Treatment of obese mice with ADSC-derived exosomes improves insulin sensitivity and alleviates obesity and hepatic steatosis." (PMID 39872218, 2024). "The link between obesity and insulin dysfunction is similar to the mechanisms presented above for humans." (PMID 38473112, 2024). "Despite ongoing debates, the carbohydrate-insulin model revealed that a high-refined carbohydrate diet can cause rapid spikes in blood sugar levels, causing elevated insulin secretion, which may promote fat deposition and inhibit fat breakdown, raising the risk of obesity." (PMID 39599620, 2024). "To date, a few bacterial strains have been found to improve insulin sensitivity and glycemic variability in metabolic syndrome, obesity and T2D." (PMID 39064765, 2024). "Disruption of mitochondrial homeostasis induced by obesity has adverse effects on lipid metabolism, adipocyte differentiation, oxidative capacity, inflammation, insulin sensitivity, and thermogenesis." (PMID 38786764, 2024). "The composition of the gut microbiota varies by sex hormones, dysregulation of the Hypothalamic-Pituitary-Adrenal (HPA) axis and insulin, feeding behavior, and obesity." (PMID 38585653, 2024). "Obesity is considered to promote PI3K/Akt signaling through mechanisms involving increased levels of insulin and leptin, and possible relationships between obesity, IGFBP7 expression, and ganitumab sensitivity deserve further study." (PMID 39362991, 2024). "It has been found that metabolic factors such as insulin and glucose can negatively influence cathelicidin expression in adipocytes, suggesting a link between obesity, IR, and the reduced ability of AT to participate in the defense against infections." (PMID 39728453, 2024). "In fact, the interplay between oxidative stress and inflammation is pivotal in the development of obesity-related complications due to the direct damage to insulin-sensitive tissues." (PMID 39334752, 2024). "In obesity men are more insulin resistant than women owing to a less efficient inhibition of fat cell lipolysis." (PMID 38491191, 2024). "RYGB is an effective obesity treatment, and patients experience rapid changes in weight and improvements in glycemic control and insulin sensitivity." (PMID 37752366, 2024). "Glucagon-like peptide-1 (GLP-1) receptor agonists treat type 2 diabetes (T2D) and obesity through mechanisms including inhibition of glucagon secretion, food intake, and gastric emptying, as well as stimulation of insulin secretion." (PMID 39931650, 2024). "Mice with targeted deletion of the SCD gene exhibited reduced body fat rate, increased insulin sensitivity, and resistance to obesity induced by a high-fat or high-carbohydrate diet." (PMID 38254437, 2024). "ABCG1 is a gene encoding the protein for triglyceride metabolism, and its methylation is related to hypertriglyceridemia, glucose metabolism, and insulin sensitivity, which promotes obesity, T2DM, and hyperlipidemia." (PMID 39200098, 2024).
Obesity (continued). "Adipocytes in mice, featuring transgenic overexpression of BMP4 under the Fabp4 promoter, display browning of inguinal WAT, increased energy expenditure and protection against high-fat diet-induced obesity, coupled with enhanced insulin sensitivity." (PMID 38826152, 2024). "In this review, we report that obesity-induced disruption of mitochondrial homeostasis adversely affects lipid metabolism, adipocyte differentiation, oxidative capacity, inflammation, insulin sensitivity, and thermogenesis in thermogenic fat." (PMID 38786764, 2024). "A 10% weight reduction improved IR and restored insulin sensitivity in patients with obesity and T2DM." (PMID 38392069, 2024). "Our study found that women and men with obesity had higher median fasting glucose and insulin levels compared to women and men with normal body weight." (PMID 39769504, 2024). "Further, the effects of polyphenols on insulin highlight their potential significance in obesity, because insulin is a crucial neurohormone in the etiology of obesity." (PMID 38397458, 2024). "As recently published, 8 months of HFD-feeding induced obesity, decreased insulin sensitivity, hyperinsulinemia and hyperglycemia." (PMID 38424560, 2024). "Nowadays, researchers in the field of small molecule medicinal chemistry and gene therapy are making efforts to develop new drugs that effectively overcome insulin resistance and counteract obesity." (PMID 38931457, 2024). "Glycodeoxycholic acid was negatively correlated with insulin clearance, and patients with obesity generally exhibited lower insulin clearance." (PMID 38375198, 2024). "Higher white blood cell counts were observed in people with obesity, except for those in the insulin-sensitive group who displayed similar WBC counts as the nOB." (PMID 38397455, 2024). "Because obesity has a very strong effect on insulin action we subdivided the participants according to body mass index (BMI) of 30 kg/m2 as cut-off value for obesity." (PMID 38491191, 2024). "NOX4-ROS contributes to this low-grade inflammation in AT, where inflammation drives obesity-induced impairment of insulin signaling." (PMID 39188529, 2024). "Obesity increases glomerular filtration due to the activation of renal sympathetic activity, renin-angiotensin-aldosterone system, and insulin resistance." (PMID 39117944, 2024). "The change of GDCA and TDCA was negatively correlated with obesity-related phenotypes, whereas positively correlated with insulin sensitivity and ANGPTL4 levels." (PMID 38409604, 2024). "Children with overweight or obesity are hyperinsulinemic and have approximately 40% less insulin-stimulated glucose than children with a normal weight." (PMID 38388431, 2024). "From a clinical perspective, no known studies have aimed to compare the metabolic effects of MICT and HIIT in the insulin-sensitive tissues of people with obesity, particularly in candidates to undergo bariatric surgery." (PMID 38892984, 2024). "As obesity increases serum testosterone, insulin, and luteinizing hormone levels, the introduction of recombinant irisin significantly lowered the serum luteinizing and insulin levels in female obese mice." (PMID 39456155, 2024). "Recent research has identified a distinct subset of women with GDM and obesity, referred to as Gestational Diabesity, which appears to involve differences at the fetoplacental level (e.g., placental insulin sensitivity, nutrient transport)." (PMID 39736862, 2024). "To conclude, insulin signaling and glucose metabolism are significantly coupled with several of the changes in brain metabolites that occur in obesity." (PMID 37824728, 2024). "CS patients commonly exhibit a range of metabolic disorders, spanning from obesity to insulin dysregulation." (PMID 38792950, 2024). "Elevated glucose and insulin in obesity increase the release of adipocyte-derived exosomes carrying Sonic Hedgehog and miR-34a, both of which promote M1 polarization." (PMID 39063184, 2024).